C10orf62 (chromosome 10 open reading frame 62)
Synonyms: bA548K23.1
Tractability: No criterion of Open Targets' tractability assessment is met for any kind of drug.
Gene: Protein-coding gene on chromosome 10 (97,589,721 to 97,590,934, forward strand). Ensembl gene ENSG00000203942.
Subcellular location (Human Protein Atlas): Cytosol; Nucleoplasm; Vesicles
Gene Ontology:
Molecular function: protein binding
Genetic constraint (gnomAD): Loss-of-function variants: 1 observed, 0.44 expected, observed/expected ratio (o/e) 2.28. That is too few expected variants to judge how well the gene tolerates losing a copy. Missense variants: 279 observed, 296.25 expected, observed/expected ratio (o/e) 0.94, 90% interval 0.85 to 1.04. Synonymous variants: 94 observed, 115.27 expected, observed/expected ratio (o/e) 0.82, 90% interval 0.69 to 0.97.
Homologues: Orthologues: dog C10orf62 (63% identical), guinea pig C10orf62 (62% identical), mouse 4933411K16Rik (57% identical), rat MGC93861 (57% identical).